ENSG00000276470
Gene: Miscellaneous RNA gene on chromosome 1 (11,843,812 to 11,843,984, forward strand). Ensembl gene ENSG00000276470.
Gene Ontology:
Molecular function: mRNA binding
Biological process: regulation of gene expression